AKT1 (AKT serine/threonine kinase 1)
Diseases named in the same sentence as AKT1 in open-access papers (continued):
Sharing a sentence is not in itself a finding about the gene and the disease.
tumor (continued). "Consequently, AKT1 is viewed as a critical factor in tumor advancement." (PMID 38360888, 2024). "However, our finding along with those of other researchers reveal that the inhibition of AKT1 also promotes tumor metastasis, which clearly justifies further investigations and calls for reevaluation of some AKT‐targeting therapeutic strategies currently under development." (PMID 37296072, 2023). "In addition, it is known that AKT1 activity influences radiosensitivity of tumor cells." (PMID 37483521, 2023). "Lastly, co-expression of MAPK4D254A and AKT1-DD only partially recapitulated the tumor-promoting activity of WT MAPK4 in the soft-agar assays, suggesting that MAPK4 activation of additional signaling cascade beyond PDK1 and AKT may be important to promote tumor cell anchorage-independent growth." (PMID 37531320, 2023). "We found that ATK1 was significantly enriched in tumors after PARPi application, and the residual tumor cells after PARPi administration were mostly drug-resistant cells after drug screening, which indicated that AKT1 enrichment might be related to PARPi resistance." (PMID 36230574, 2022). "Moreover, PTEN abnormalities had been detected by protein loss rather than by the presence of genomic alterations, and tumours had not been examined for AKT1 mutations." (PMID 35671774, 2022). "Detection of at least one PI3K/AKT/PTEN pathway alteration in baseline plasma sample was not correlated with response to treatment when assessed alone (P = 0.70) or in combination with tumor status (PIK3CA or AKT1 mutations or PTEN deletion, P = 1)." (PMID 35122700, 2022). "Therefore, our study suggests that macrophages could be educated and polarized to M2 through fine‐tuning Akt1 SUMOylation by SENP3 in response to tumor environment factors." (PMID 33932085, 2022). "Interestingly, recent work has described small-molecule inhibitors that may be capable of targeting pathogenic AKT isoforms only (AKT1 and AKT2) while leaving the tumor-suppressive functionality of AKT3 intact." (PMID 34771532, 2021). "Similarly, Akt1 depletion in yki3S/A cells led to a complete suppression of yki3S/A tumor growth." (PMID 34078667, 2021). "Moreover, knockdown of PRMT5 significantly suppressed tumor growth, which could be reversed by myr-AKT1." (PMID 34103528, 2021). "However, systemic deletion of Akt1 but not Akt2 inhibited lung metastasis through impairment of mobilization and survival of tumor-associated neutrophils and neutrophil-specific deletion of Akt1 suppressed metastasis." (PMID 34298660, 2021). "However, tumor associated neutrophils were not present after Akt1 systemic deletion, indicating that inhibition of Akt1 prevented prometastatic neutrophils from promoting metastasis." (PMID 35578699, 2021). "However, patients with AKT1 mutations did not statistically differ from AKT1 WT patients in terms of age, tumor size, lymph node metastasis, and Ki67 score." (PMID 34093841, 2021).
tumor (continued). "In addition, reducing Akt1 expression to enhance radiotherapy may lessen the number of treatments required to induce apoptosis or arrest tumor growth, potentially making radiation more tolerable for TNBC patients." (PMID 32438621, 2020). "Finally, we examined the effect of circ-AKT1 on the tumor growth of CC in animal models." (PMID 32193155, 2020). "Also, the tumor growth in mice was facilitated by circ-AKT1 overexpression." (PMID 32193155, 2020). "However, in the same tumours, AKT1 silencing had growth-suppressive effects." (PMID 32453400, 2020). "In SW480 cells, CMTM4 expression was found to be inversely related to the phosphorylation of AKT1, and the tumor-suppressive functionalities observed with CMTM4 overexpression could be mimicked in the CMTM4- SW480 cell line by direct chemical inhibition of AKT using LY294002." (PMID 33614606, 2020). "In addition, PTEN is a tumor suppressor and is modified by methylation and mutation to induce the reduction of its expression, thus boosting the activity of the downstream PIK3CA and AKT1." (PMID 31126066, 2019). "Therefore, it is possible that Akt1 may serve as a potential drug target in other tumour types, including PCa." (PMID 30872976, 2019). "Furthermore, apoptosis is inhibited by AKT1 fostering the induction of tumor growth." (PMID 31752925, 2019). "Therefore, the plasmid doses in HDI may affect the integration efficiency of the sleeping beauty transposon, which could lead to differential tumor progression in this Akt1/N-Ras HCC mouse model." (PMID 30526672, 2018). "The mutations in this tumor included 3 predicted high impact mutations in MTOR a regulator of stress response, OGT a glycosyltransferase that modifies a broad range of targets including H2B, AKT1, EZH2, PFKL, KMT2E/MLL5, MAPT/TAU and HCFC1, and FAM129B a negative regulator of apoptosis." (PMID 28415633, 2017). "Furthermore, they suggested that Akt1 could affect tumour cell invasion via phosphorylation of focal adhesion kinase (FAK)." (PMID 27661110, 2016). "Eighty-two (11.7 %) samples had not sufficient tumor content according to pathologic examination, and thus could not be evaluated for AKT1 mutations." (PMID 27515171, 2016). "In addition, transgenic mice harboring a phospho-mimetic AKT1(T308D/S473D) mutant in combination with HER2 display a decrease in tumor latency and accelerated tumor growth, but decreased incidence of metastases, consistent with AKT1 functioning as a metastasis suppressor." (PMID 27004402, 2016). "Hence, our results suggest that the tumor-suppressing effects of miR-495 in ESCC might be a consequence of its ability to decrease Akt1 expression." (PMID 27323412, 2016). "Our results suggest that miR-495 may act as a tumor suppressor by targeting Akt1 in ESCC." (PMID 27323412, 2016). "Altogether, these results indicate that aberrant signalling through the PI3K pathway – induced by mutant Akt1, PIK3CA or by PTEN loss - significantly increases the percentage of cells able to initiate in vitro growth as spheroids enriched in TICs that efficiently support tumor growth in vivo." (PMID 26486080, 2015). "Of the single MSI-H tumor with an AKT1 mutation, PIK3CA and PTEN were not mutated." (PMID 26517354, 2015). "The 8 SNPs (CD3EAP rs967591, TNFRSF10B rs1047266, AKT1 rs3803300, C3 rs2287845, HOMER2 rs1256428, GNB2L1 rs3756585, ADAMTSL3 rs11259927, and CD3D rs3181259) were found to be significantly associated with OS and/or DFS when adjusted for age, gender, smoking status, tumor histology, pathologic stage." (PMID 26462029, 2015). "Therefore, Akt1 and/or Erk1/2 signaling pathways might also be involved in the anti-tumor effects of fenofibrate in MDA-MB-231 cells." (PMID 24529079, 2014).
tumor (continued). "Hence, known oncogenic mutations in PIK3CA (exons 10 and 21) and AKT1 (exon 2) were screened in tumor DNA with negative results, which suggests that the responsible somatic event(s) is a different, uncommon one." (PMID 24498881, 2014). "Finally, we see a slight compensatory increase in Akt1 expression in the uninfected and tumor bearing Akt2−/− and Akt3−/− mice, which could contribute to the accelerated tumor development in these mice." (PMID 24722238, 2014). "Moreover, during tumor development, Akt1 and Akt2 often act in a complementary opposing manner." (PMID 32309540, 2013). "On the other hand, down-regulation of Oct-4 expression has been shown to induce apoptosis of tumor-initiating-cell-like cells through an Oct-4/Tcl1/Akt1 pathway, implying that Oct-4 might maintain the survival of tumor-initiating cells, at least in part, by inhibiting apoptosis." (PMID 22300949, 2012). "Notably, from the integrated analysis of the TMAs we found that AKT activation was more frequently observed in tumours showing aberrant expression of more than a single gene within the PI3K pathway (PTEN loss, or overexpression of AKT1, AKT2, p110α respectively)." (PMID 22363436, 2012). "Moreover, they all significantly positively correlated with tumour grade, suggesting that Akt1 pathway might be involved in tumour progression." (PMID 21407808, 2011). "These two AKT1 mutant tumours do not possess any mutations in PIK3CA, PTEN and K-Ras." (PMID 19491896, 2009). "Our results and earlier reports suggest that AKT1 mutations might be mutually exclusive with other PI3K–AKT-activating alterations, although PIK3CA mutations frequently coexist with other alterations (such as HER2, K-Ras and PTEN) in several types of tumours." (PMID 19491896, 2009). "As in case of Akt-1, we could not find any significant association of pAkt with nodal status, tumour size, ER, PgR or Bcl-2 but we did find a strong negative association with SPF." (PMID 11870534, 2002). "In the TCGA CCA cohort, high expression of IL6, TNF, AKT1, and STAT3 and low expression of PPARG correlated with advanced tumor stage and poorer overall survival (e.g., IL6: ρ = 0.42, p = 0.01)." (PMID 41899527, 2026). "Collectively, these findings demonstrate that inhibiting AKT1 reverses GRP78-mediated cell migration and tumor metastasis by upregulating ΔNp63α." (PMID 40223122, 2025). "The majority of DEGs related to this pathway (ITGAV, KDR, VEGFB, AKT1, VEGFA) were downregulated in tumor cells except for HSBP1 and SHC2." (PMID 39245631, 2025). "Immune alterations also include increased CD4 +/CD8 + and IL-17 + γδ T cells, and elevated expression of immunosuppressive (IDO1, IL-10, PD-L1) and oncogenic (AKT1, STAT3, CXCR4) genes with key roles in tumor progression and immune evasion." (PMID 40924302, 2025). "Tumor growth was monitored, and molecular analyses included RNA sequencing and immunofluorescence quantification of PI3K, AKT1, mTOR, ERBB2, BRAF, and MITF protein levels, and molecular docking simulations were performed." (PMID 40806647, 2025). "Molecular analyses of tumor tissues confirmed a marked reduction in both FLOT2 and AKT1 expressions in the treated group." (PMID 41264121, 2025). "Hyperactivation of AKT1 is observed in over 50% of human tumors, and our previous study demonstrated that AKT1 plays a central role in transducing oncogenic signals (including, PI3K, Ras and Her2) to promote tumor metastasis by suppressing ΔNp63α expression." (PMID 40223122, 2025). "It is shown that IL-6 produced by MSCs increases endothelin 1 (ET-1) expression in colorectal cancer (CRC) cells, resulting in the activation of AKT1 and ERK in endothelial cells which lead to tumor neo-angiogenesis enhancement." (PMID 39981232, 2025). "The PI3K/AKT pathway, comprising components such as PIK3CA, AKT1, PTEN, and mTOR signaling complexes, plays a complementary role in tumor progression." (PMID 41462994, 2025).
tumor (continued). "Increased activation of this pathway, observed in our study through elevated AKT1 and BRCA1 expression, can lead to enhanced tumor cell survival and resistance to apoptosis." (PMID 40584614, 2025). "Capivasertib–fulvestrant is approved in Japan for the treatment of patients with one or more tumor biomarker alterations (PIK3CA, AKT1 or PTEN)." (PMID 39379782, 2025). "NF2 tumours exhibited more immune cells than AKT1 E17K or KLF4 K409Q, and AKT1 E17K showed slightly higher immune cell counts than KLF4 K409Q." (PMID 40420192, 2025). "It sponges miR‐942‐5p to increase AKT1 expression, a non‐canonical mediator of TGF‐β signaling to promote EMT and tumor growth." (PMID 40356340, 2025). "UMAP distribution showed that AKT1 and ESR1 were primarily expressed in tumor cells, SRC and IL6 were concentrated in the Myeloid subpopulation, while MTOR and HIF1A exhibited a broader distribution across multiple cell types." (PMID 40746726, 2025). "PDGFRA activation leads to phosphorylation of PIK3R1, triggering downstream signaling cascades including calcium mobilization and activation of PKC, AKT1, HRAS/MAPK/ ERK, and STAT pathways, thereby promoting tumor growth and survival." (PMID 41426972, 2025). "Beyond capivasertib and ipatasertib, other AKT inhibitors under development for pan-tumor indications include miransertib (NCT01473095), BAY 1125976 (NCT01915576), an AKT1/2 inhibitor, and TAS0612 (NCT04586270), which targets RSK/AKT/S6K signaling." (PMID 40576713, 2025). "Increasing evidence highlights the distinct roles of AKT1, AKT2, and AKT3 in tumor progression and radiation resistance." (PMID 40725100, 2025). "In BLC, NAT10 promotes tumor growth by upregulating key oncogenes such as B-cell CLL/lymphoma 9-like (BCL9L), SOX4, and AKT1 through ac4C modification." (PMID 41446042, 2025). "Testing for PIK3CA/AKT1/PTEN alterations was carried out using FoundationOne®CDx, a tumor tissue-based next-generation sequencing (NGS) test, for all patients except those enrolled in China, where OncoScreen Plus® was used instead." (PMID 40597213, 2025). "In this study, pharmacologic inhibition AKT1 reversed GRP78-mediated downregulation of FOXO3a and ΔNp63α expression, thereby inhibiting cell migration and tumor metastasis." (PMID 40223122, 2025). "Proteomic profiling further revealed its impact on multiple oncogenic and tumor-suppressive proteins, with notable upregulation of SERPINB2, KIT, and NOTCH1, alongside downregulation of COX2, DNMT1, MAPK1, AKT1, MKI67, EP300, and SMC1A." (PMID 41321870, 2025). "In the In Vivo model, the combination therapy significantly reduced AKT1 and PD‐L1 expression in the TME, contributing to inhibition of tumor progression and immune evasion." (PMID 40553053, 2025). "DNAJB6 exerts a dual tumor-suppressive role by stabilizing GPX4 and activating the signaling AKT1 pathway." (PMID 41293165, 2025). "AKT1 and PRKCB have the strongest binding ability to AA and are important proteins for AA to exert anti-tumor effects." (PMID 41011581, 2025). "Consistent with the tumor inhibitory effect of FZD6 knockdown, the activities of proteins that promote tumor growth including SRC, AKT1, and STAT3 were decreased." (PMID 41286306, 2025). "The mRNA expression of RXRα, AKT1, ESR1, MAPK1, and HSP90AA1 was analyzed in different tumor tissues." (PMID 38835342, 2024). "Signaling pathways involving AKT1 and MAP3K1 influence cell survival and apoptosis, enhancing tumor growth when activated." (PMID 39273340, 2024). "MiR-422a inhibits tumor development and cell proliferation in colorectal cancer via binding to the 3′-UTR of AKT1." (PMID 38836981, 2024). "AKT monotherapy activity in PTEN protein deficient solid and haematological tumour cell lines is expected, as well as in tumour with activating alteration in PIK3CA and AKT1." (PMID 39284898, 2024).
tumor (continued). "CCND1, AKT1 and CD44 were all expressed at significantly higher levels in the tumour compartment of p16-/HPV- relative to p16+/HPV+ OPC, with CCND1 also being upregulated in the stromal compartment." (PMID 39328208, 2024). "In the BRAF and RNF43 tumours, co-occurring mutations were observed in ACVR2A (FDR-adjusted P = 0.06) in HM tumours, and AKT1 (FDR-adjusted P = 0.03) and TYRO3 (FDR-adjusted P = 0.08) in the nHM tumours." (PMID 39112715, 2024). "Among others, CysGCA 5'-half and LysCTT 3'-tRF were upregulated in the tumor samples, and corresponded to decreased expression of PIK3R1, AKT1, and CPEB3." (PMID 39317063, 2024). "4‐Ac‐GABA activates GABAAR on CD8+ T cells to inhibit AKT1 signaling, CD8+ T cell activation, and anti‐tumor response." (PMID 39325640, 2024). "The present study correlates the expression levels of critical genes (PIK3CA, PTEN, AKT1, FOXO1, and FRAP) in 60 tumor tissues with clinicopathological and demographic characteristics." (PMID 38891994, 2024). "Meanwhile, three targeted genes (AKT1, MTOR and PIK3CG) of these drugs showed significant upregulation in SLC12A5‐low tumour." (PMID 38685685, 2024). "Using the GEPIA2 web tool, AKT1, MAPK1, and mTOR expression levels were compared between PDAC and a normal population (for tumor tissues, n = 197, and for normal tissues, n = 171)." (PMID 38553450, 2024). "Especially, the therapeutic mechanisms were resolved, where inhibiting mitochondrial pathway and activating AKT signaling pathway including AKT-1, HMOX-1 and NRF-2 were found to be responsible for the excellent anti-tumor consequences." (PMID 39014402, 2024). "Yet, silencing of ME2 apparently reduced the tumor growth derived form PTEN-depleted cells, further reinforcing the importance of ME2 in AKT1-mediated tumor growth." (PMID 38263319, 2024). "The mRNA expression of RXRα, AKT1, ESR1, MAPK1, and HSP90AA1 in tumor and normal tissues was analyzed using the GEPIA database." (PMID 38835342, 2024). "Several genes associated with tumour cell proliferation and survival (CCND1, AKT1 and CD44) were more highly expressed in p16-/HPV- tumours relative to p16+/HPV+." (PMID 39328208, 2024). "Oncogenes (e.g., NOTCH1 and ERBB2) tended to increase in centrality in tumor modules while tumor suppressors (e.g., BAP1, AKT1, and EP300) decreased in centrality." (PMID 38685127, 2024). "Single-cell RNA-seq analysis revealed the enrichment of mTORC1 signaling gene clusters in tumor cells expressing ONECUT2, and AKT1 expression was observed in epithelial cells." (PMID 38997271, 2024). "Here, we discovered a previously unrecognized mechanism by which tumor cells coordinate glycolysis and the mitochondrial TCA cycle via AKT1-mediated ME2 phosphorylation." (PMID 38263319, 2024). "Fifth, it has been demonstrated that inhibiting both AKT1 and AKT2 is essential for obtaining a greater sensitization of tumor cells to apoptotic stimuli and reduceing AKT phosphorylation in vivo." (PMID 37513905, 2023). "Mechanistically, secreted IGFBP1 activates mitochondrial superoxide dismutase (SOD2) by preventing AKT1‐mediated SOD2 phosphorylation, thereby promoting metastasis by sustaining tumor cell survival during confined migration." (PMID 37296072, 2023). "Using the GEPIA2 website, AKT1, MAPK1, and mTOR expression levels were compared between PDAC and a normal population (for tumor tissues, n = 197, and for normal tissues, n = 171)." (PMID 37503215, 2023). "AKT1, as a growth inducer, promotes tumour cell growth but damages metastasis, while AKT2 can increase tumour cell invasion and metastasis." (PMID 37489050, 2023). "PTHrP ablation leads to a significant decrease in tumor growth and metastasis as well as the reduced expression of several factors known to support tumor progression, including: CXCR4, Ki67, Bcl-2, AKT1, and Cyclin D1." (PMID 38435029, 2023).